GCG (glucagon)
Diseases named in the same sentence as GCG in open-access papers (continued):
Sharing a sentence is not in itself a finding about the gene and the disease.
type 2 diabetes (continued). "Therefore, alterations of Sumo2 in alpha cells could affect alpha cell glucagon secretion via similar mechanisms and promote type 2 diabetes pathogenesis." (PMID 39508880, 2025). "Future studies on glucagon kinetics may therefore focus on type 2 diabetes patients separately." (PMID 38681771, 2024). "Type 2 diabetes is associated with increased alpha-cell secretion of glucagon, leading to inappropriately elevated plasma glucagon in both the non-fasted and fasted states, and impaired glucose-mediated glucagon suppression." (PMID 38612880, 2024). "In our study, except for Cushing's syndrome, we also found the Glucagon signaling pathway in DE lncRNAs-enriched pathways and Type II diabetes mellitus in DE miRNA-enriched pathways, suggesting HYJJ might have regulation in CHF induced by Cushing's syndrome-related Type II diabetes." (PMID 36704572, 2023). "Dysfunction of alpha- and beta-cells in type 1 diabetes (T1D) and type 2 diabetes (T2D) patients manifests as inappropriate glucagon response, and during hypoglycaemia glucagon has been identified as a major player during counter-regulation." (PMID 35327658, 2022). "In conclusion, it is likely that glucagon test is the most powerful tool for predicting the possibility of insulin withdrawal as well as for evaluating endogenous insulin secretory capacity in subjects with type 2 diabetes requiring hospitalization due to hyperglycemia." (PMID 35574023, 2022). "Thus, due to its fundamental role in promoting hepatic glucose production, therapeutic strategies aimed at both activating the GCGR to acutely rescue from hypoglycemia and at blocking glucagon-mediated hyperglycemia for the treatment of type 2 diabetes (T2D) have been pursued." (PMID 35547006, 2022). "People with impaired glucose tolerance/type 2 diabetes, typically have elevated fasting levels of glucagon and may show increasing levels of glucagon during the 1st h of the OGTT and the suppression is typically delayed, but the same low levels are normally reached after 2–3 h." (PMID 35990325, 2022). "In type 2 diabetic patients, RN has been shown to offer a variety of effects, including lowering blood glucose and glycosylated haemoglobin levels, promoting insulin release, and decreasing glucagon synthesis, therefore improving pre- and postprandial blood glucose." (PMID 36233271, 2022). "Thus, body weight may be one of the determinants of postprandial glucagon levels in type 2 diabetes." (PMID 34382579, 2021). "Moreover, branched-chain amino acids do not stimulate glucagon secretion but are associated with insulin secretion in type 2 diabetes." (PMID 34382579, 2021). "Thus, a robust increase in hepatic glucose release, next to a rise in plasma glucose levels, was observed in subjects diagnosed with type 2 diabetes upon intense exercise in the fasted state as a consequence of aberrant increments of plasma epinephrine and glucagon synthesis." (PMID 33356015, 2021). "However, glucagon hypersecretion contributes to the pathogenesis of type 2 diabetes." (PMID 32774668, 2020). "If pancreatic islet GABA concentration changes out of the physiological range or the pulsatile GABA release is disturbed, it may impair proper insulin and glucagon secretion, potentially alter cell fate and eventually contribute to pathogenesis of type 2 diabetes." (PMID 31963438, 2020). "Interestingly, each group of comparisons are all connected to the factors affecting the regulation of blood glucose, such as the Insulin signaling pathway, Insulin resistance, the Glucagon signaling pathway, Type II diabetes mellitus, and Type I diabetes mellitus." (PMID 32041309, 2020). "Whether glucagon counter-regulation to hypoglycemia is affected during DPP-4 inhibition in type 2 diabetes has been studied in drug-naïve subjects, in subjects when a DPP-4 inhibition was added on to insulin therapy, and in elderly subjects with metformin-treated type 2 diabetes." (PMID 31275243, 2019).
type 2 diabetes (continued). "The secretion of glucagon is complex and involves a combination of various factors; defective suppression of glucagon by glucose or insulin and especially insulin resistance in α-cells have been suggested as potential mechanisms for the hyperglucagonemia in type 2 diabetes." (PMID 31546230, 2019). "A study population of 375 healthy subjects at increased risk for type-2 diabetes, phenotyped by a 5-point oral glucose tolerance test (OGTT) and genotyped for recently described SLC5A2 tagging single nucleotide polymorphisms (SNPs), was selected for plasma glucagon measurements." (PMID 28472182, 2017). "Dyslipidemia, dysregulated adipokine secretion and alteration in glucagon and adropin concentrations are important obesity-related factors in the pathophysiology of human Type 2 diabetes; however, their roles in the pathophysiology of feline diabetes mellitus are relatively unknown." (PMID 28376869, 2017). "However, evidence started to mount that glucagon might also play a role in the hyperglycemia of type 2 diabetes, including important pioneering studies from the laboratories of Alain Baron and Robert Rizza." (PMID 28323959, 2017). "Interestingly, it has recently been reported that the well-known disturbed pulsatility of insulin secretion in type 2 diabetes is concomitant with disturbed glucagon pulsatility (higher pulse mass in patients with type 2 diabetes), possibly contributing to the hyperglucagonemia in these patients." (PMID 25961284, 2015). "It has been recognized that the concerted actions of insulin and glucagon keep plasma glucose levels normal, and that any imbalance in the actions of these molecules can contribute to an increased demand for insulin, impaired glucose tolerance, and persistent hyperglycemia in type 2 diabetes." (PMID 26378455, 2015). "The opposite effects of insulin and glucagon in fuel homeostasis, the paracrine/endocrine inhibitory effects of insulin on glucagon secretion and the hyperglucagonemia in the pathogenesis of type 2 diabetes (T2D) have long been recognized." (PMID 25177371, 2014). "The authors concluded that post-glucagon C-peptide estimation was a good predictor of Nigerians with type 2 diabetes who will likely require insulin for control and a single estimation of post-glucagon C-peptide levels may be a useful guide in predicting likelihood of the need for insulin." (PMID 25945127, 2014). "The potential of reducing glucagon secretion (e.g. using GLP-1) or inhibiting glucagon action (e.g. with glucagon receptor antagonists) have received much attention as therapeutic strategies for the treatment of excess glucose production in type 2 diabetic patients." (PMID 22479612, 2012). "The additional properties of inhibition of glucagon secretion and inhibition of caloric intake accelerated the development of GLP-1 receptor agonists for usage in type 2 diabetes management." (PMID 40149944, 2025). "Cells co-expressing β-cell markers (insulin, Nkx6.1, PDX1, PC1/3, GLUT1) together with α-cell markers (glucagon, ARX, GLP-1, GC), in various combinations, have been identified in individuals with both type 1 and type 2 diabetes." (PMID 41598174, 2025). "In patients with type 2 diabetes (T2D), pancreatic alpha cells lose the ability to respond to changes in the circulating glucose levels and glucagon secretion becomes dysregulated by unknown mechanisms." (PMID 41308986, 2025). "In obese or overweight individuals with type 2 diabetes, a GLP‐1/glucagon co‐agonist decreased hepatic fat content, and in mice with diet‐induced MASH the co‐agonist reduced body weight and liver TG concentrations." (PMID 39985139, 2025). "In order to investigate IGFBP7 expression in islet cells at the protein level, we immunostained pancreatic sections from ND donors and type 2 diabetes donors for IGBFP7, glucagon, and insulin (for donor information)." (PMID 39280605, 2024).
type 2 diabetes (continued). "PTDM shares many characteristics with type 2 diabetes mellitus (T2DM), such as impaired insulin release and impaired suppression of glucagon release." (PMID 38352660, 2024). "This study explored the correlation between pancreatic islet α cell function, as reflected by the plasma glucagon levels, and Diabetic Peripheral Neuropathy (DPN) in patients with Type 2 Diabetes Mellitus (T2DM)." (PMID 38908048, 2024). "In this study, we demonstrated that inhibition of glucagon activity by GCGR mAb not only improved blood glucose control but also increased pancreatic beta cell mass and proliferation in mouse models of type 2 diabetes." (PMID 36331598, 2023). "Although insulin and glucagon play opposite regulatory roles both in normal metabolic homeostasis and dysfunction in type 2 diabetes, PWS mice are remarkable in having low blood levels of both insulin and glucagon." (PMID 37068109, 2023). "The data are cross-sectional, and larger, longitudinal and interventional studies are needed to establish a contribution by glucagon and HPA axis dysregulation in the development of insulin resistance and type 2 diabetes." (PMID 36752854, 2023). "In SGLT2-treated type 2 diabetic patients with euglycemic DKA, there is a lower insulin-to-glucagon ratio due to this increased glucosuria which stimulates lipolysis." (PMID 35251838, 2022). "Type 2 diabetes mellitus (T2DM) is a progressive metabolic disorder characterized by hyperglycemia resulting from the combination of resistance to insulin action, inadequate insulin secretion, and excessive or inappropriate glucagon secretion." (PMID 35409287, 2022). "Nonetheless, our results agree with previous reports showing a rise in glucagon during OGTT, in obese women with type 2 diabetes 1 month after RYGB, despite an increase in GLP-1 levels." (PMID 31983031, 2020). "Already a therapeutic target for type 2 diabetes (T2D), GLP-1 is an integral signaling hormone responsible for promoting insulin secretion and satiety while decreasing glucagon secretion and gastric emptying." (PMID 32051237, 2020). "The reduced GAPDH acetylation was also observed in the liver of obesity and type 2 diabetes mouse models, and key lysine residues in GAPDH contribute to the regulation of glucose tolerance and sensitivity to glucagon and insulin." (PMID 33043000, 2020). "In type 2 diabetes, the basal insulin secretion is impaired, and FFA and the fasting glucagon levels are high." (PMID 30871141, 2019). "At the same time, other literature reports that glucagon can bind to its receptor GCGR to regulate glucose levels and fatty acid oxidation in patients with type 2 diabetes by regulating the level of cAMPs and pka-independent pathways." (PMID 31341893, 2019). "As a result, a number of clinical studies are evaluating the potential for glucagon/GLP-1 receptor co-agonists for obesity and type 2 diabetes treatment." (PMID 31284506, 2019). "Regarding the modulation of glucagon secretion by GIP in type 2 diabetes, some studies have found that in patients with type 2 diabetes, the glucagonotropic action of GIP prevails even during hyperglycemia." (PMID 31443356, 2019). "But if the role of glucagon on type 2 diabetes is taken into account, the effect of HA1A would be important, as this receptor induces glucagon secretion and potentiates the activity of adenylyl cyclase, a mediator of the glucagon receptor signaling pathway." (PMID 30820389, 2018). "In this study we have evaluated the reciprocal modulation of glucagon and GLP-1 from alpha cells in response to metabolic and hormonal conditions that are commonly seen in type 2 diabetes." (PMID 29121068, 2017). "In type 2 diabetes mellitus (T2DM), both glucagon and insulin secretion are impaired." (PMID 28275121, 2017).
type 2 diabetes (continued). "Our data suggest that AMPK activation in the liver could be beneficial by opposing short-term glucagon action via PDE activation to reduce cAMP as a new therapeutic strategy for the treatment of metabolic diseases associated with dysregulated cAMP/PKA signalling, such as type 2 diabetes." (PMID 26952277, 2016). "In type 2 diabetes mellitus (T2DM), somatostatin lowers glucose concentrations by inhibiting glucagon secretion and abnormalities in the GH-IGF-1 axis have been associated with increased cardiovascular risk in T2DM." (PMID 25880900, 2015). "However, in patients with type 2 diabetes, plasma levels of glucagon remain abnormally high after ingestion of a meal and may contribute to impaired glucose tolerance further suggesting that the cAMP signaling pathway is upregulated in insulin-resistant individuals." (PMID 25961284, 2015). "Type 2 diabetes mellitus (T2DM) is a chronic disease characterized by hyperglycemia due to multiple dysfunctions including inadequate insulin secretion, resistance to insulin action, and excessive and inappropriate glucagon secretion." (PMID 24918743, 2014). "Elevated glucagon levels and increased hepatic glucagon receptor (GCGR) signaling contribute to hyperglycemia in type 2 diabetes." (PMID 24189067, 2013). "Glucagon is an essential regulator of hepatic glucose production (HGP), which provides an alternative therapeutic target for managing type 2 diabetes with glucagon antagonists." (PMID 23226550, 2012). "In patients with type 2 diabetes, DPP-4 inhibition leads to higher levels of active incretins, both during fasting and post meal, which in turn lead to higher insulin release, lower glucagon levels, and improved fasting and post meal glucose concentrations." (PMID 23554750, 2012). "In ambulant type-2 diabetics, exogenous GLP-1 decreases blood glucose via stimulation of insulin and suppression of glucagon secretion, as well as slowing of gastric emptying." (PMID 21255422, 2011). "However, in type 2 diabetes, both GLP-1 secretion and activity are impaired, leading to insufficient insulin release and excessive glucagon levels, which exacerbate glucose dysregulation." (PMID 40260393, 2025). "The effects of exercise on insulin and glucagon were consistent across participants with and without type 2 diabetes." (PMID 40580209, 2025). "The cephalic phase of insulin secretion is absent in type 2 diabetes, and glucagon secretion is not suppressed after eating." (PMID 40940782, 2025). "The observed lower glucagon release was not reported as an acute effect in 20 healthy men nor as a long-term effect in 17 individuals with type 2 diabetes receiving 10 mg melatonin." (PMID 40064676, 2025). "This indicates that the nervous system’s ability to suppress glucagon secretion in a manner independent of insulin during the fed state in healthy individuals is lacking in type 2 diabetes." (PMID 40940782, 2025). "The glucagon infusion decreased circulating amino acid levels similarly in all subgroups, without significant differences in the response to exogenous glucagon between individuals with and without obesity and type 2 diabetes." (PMID 38276866, 2024). "Here, we investigated circulating amino acid levels in participants with and without obesity and type 2 diabetes in both the fasting state and during an intravenous glucagon infusion (dosed to achieve high physiological plasma concentrations)." (PMID 38276866, 2024). "To further investigate this link, we measured amino acid levels in individuals with and without obesity and type 2 diabetes before and during an infusion of glucagon." (PMID 38276866, 2024). "Here, we investigated the effect of exogenous glucagon on circulating amino acids in obese and non-obese individuals with and without type 2 diabetes." (PMID 38276866, 2024). "Based on these premises, it is not surprising that glucagon plays a remarkable role in the pathophysiology of type 2 diabetes (T2D)." (PMID 38681771, 2024).
type 2 diabetes (continued). "This allows for an alternative perspective to position elevated glucagon secretion observed in type 2 diabetes as a mechanism to compensate, rather than induce, dysregulated homeostasis." (PMID 39599691, 2024). "The ingestion of a mixed-macronutrient meal augments differing temporal profiles in insulin clearance among individuals without type 2 diabetes, which is associated with HOMA-IR and the secretion of glucagon." (PMID 39138690, 2024). "The insulin (INS) gene was only expressed in pancreatic β-cells, and the glucagon (GCG) gene was only expressed in pancreatic α-cells in both nondiabetic and type 2 diabetes donors." (PMID 37147373, 2023). "Hepatic extraction, insulin secretion rates and glucagon secretion rates in people with and without type 2 diabetes." (PMID 37751301, 2023). "In individuals with type 2 diabetes who are recently diagnosed, and in those where the disease has not yet progressed to the level where the glucagon secretory capacity becomes absent, glucagon is known to be the most important counterregulatory hormone." (PMID 37308751, 2023). "This suggests that, in type 2 diabetes, β cells do not have increased dependency on glucagon signaling via the GLP1R to maintain insulin secretion." (PMID 37751301, 2023). "Type 1 and type 2 diabetes are both characterised by impaired glucagon secretion, which fails to counteract hypoglycaemia and contributes to hyperglycaemia." (PMID 36404376, 2023). "While several studies have shown that SGLT2 inhibitors increase plasma glucagon levels in patients with type 2 diabetes, this does not appear to be the case in people with prediabetes." (PMID 35120993, 2022). "EYA2 locus is associated with increased plasma glucagon levels at 30 min during OGTT, while other variants influence glucagon levels without conferring an increased type 2 diabetes risk." (PMID 36686477, 2022). "The final mechanism is slowing gastric emptying, inhibiting the inappropriate release of postprandial glucagon, and possibly inhibiting the appetite control center of the brain CLP-1 analogs are currently used for patients with type 2 diabetes (T2DM), as well as for patients with obesity." (PMID 34335269, 2021). "Taken together, altered insulin-antagonistic responses, including the cortisol axis, glucagon and ANS, in obese insulin-resistant individuals may contribute to the development of long-term dysglycaemia and, hypothetically, also type 2 diabetes." (PMID 33241460, 2021). "We reported an eight times increased frequency of insulin-positive cells co-expressing glucagon and a five times increased frequency of NKX6.1-positive, insulin-negative cells co-expressing glucagon in donors with type 2 diabetes compared to the control group." (PMID 34804002, 2021). "Our observation suggests that fasting plasma glucose is not concomitant with glucagon levels; however, glucagon suppression, after glucose intake, was dysregulated in type 2 diabetes and impaired glucose tolerance." (PMID 33758717, 2021). "Although glucagon dysregulation is as important as insulin dysregulation in type 2 diabetes, therapeutic pharmacological approaches targeting glucagon are lacking, compared with pharmacological approaches that improve insulin secretion and β-cell function." (PMID 33020399, 2020). "Higher fasting plasma glucagon levels and the lack of its postprandial suppression or even enhanced secretion were shown in subjects with type 2 diabetes." (PMID 32411223, 2020). "Our group has studied the separate and combined effects of GIP, GLP-1 and GLP-2 (the latter known to be glucagonotropic but without any notable effect on insulin secretion) on glucagon secretion in 10 patients with type 2 diabetes." (PMID 31443356, 2019). "To date, type 2 diabetes is considered to be a “bi-hormonal disorder” rather than an “insulin-centric disorder,” suggesting that glucagon is as important as insulin." (PMID 31357734, 2019).